ATXN10 (ataxin 10)
Description:
May play a role in the regulation of cytokinesis. May play a role in signaling by stimulating protein glycosylation. Induces neuritogenesis by activating the Ras-MAP kinase pathway and is necessary for the survival of cerebellar neurons (By similarity). Does not appear to play a major role in ciliogenesis (By similarity).
Synonyms: SCA10; E46L; FLJ37990; ATX10; HUMEEP
Tractability: Antibody: its Gene Ontology location is reachable by antibodies, with high confidence; the Human Protein Atlas places it where antibodies can reach. PROTAC: UniProt records ubiquitination sites on it; ubiquitination databases record sites on it; its protein half-life has been measured.
Gene: Protein-coding gene on chromosome 22 (45,671,798 to 45,845,307, forward strand). Ensembl gene ENSG00000130638.
Subcellular location: Cytoplasm, perinuclear region; Midbody; Cytoplasm, cytoskeleton, cilium basal body; Cytoplasm, cytoskeleton, microtubule organizing center, centrosome, centriole
Subcellular location (Human Protein Atlas): Plasma membrane; Cytosol; Primary cilium
Gene Ontology:
Molecular function: protein binding
Biological process: nervous system development; neuron projection development; regulation of cytokinesis; plasma membrane bounded cell projection organization
Cellular component: cytoplasm; dendrite; extracellular region; membrane; midbody; neuronal cell body; perinuclear region of cytoplasm; centriole; ciliary basal body; cytosol; plasma membrane bounded cell projection
Genetic constraint (gnomAD): Loss-of-function variants: 26 observed, 50.15 expected, observed/expected ratio (o/e) 0.52, 90% interval 0.38 to 0.72. The upper end of that interval is the gene's LOEUF score, 0.72, which puts it in group 2 of 6, group 1 being the genes least tolerant of losing a copy. Missense variants: 556 observed, 581.8 expected, observed/expected ratio (o/e) 0.96, 90% interval 0.89 to 1.02. Synonymous variants: 224 observed, 226.18 expected, observed/expected ratio (o/e) 0.99, 90% interval 0.89 to 1.11.
Homologues: Orthologues: chimpanzee ATXN10 (99% identical), dog ATXN10 (89% identical), guinea pig ATXN10 (87% identical), rat Atxn10 (84% identical), macaque ATXN10 (84% identical), mouse Atxn10 (83% identical), pig ATXN10 (76% identical), tropical clawed frog atxn10 (47% identical), zebrafish atxn10 (36% identical).